PGAM5 (PGAM family member 5, mitochondrial serine/threonine protein phosphatase)
Description:
Mitochondrial serine/threonine phosphatase that dephosphorylates various substrates and thus plays a role in different biological processes including cellular senescence or mitophagy. Modulates cellular senescence by regulating mitochondrial dynamics. Mechanistically, participates in mitochondrial fission through dephosphorylating DNM1L/DRP1. Additionally, dephosphorylates MFN2 in a stress-sensitive manner and consequently protects it from ubiquitination and degradation to promote mitochondrial network formation. Regulates mitophagy independent of PARKIN by interacting with and dephosphorylating FUNDC1, which interacts with LC3. Regulates anti-oxidative response by forming a tertiary complex with KEAP1 and NRF2. Regulates necroptosis by acting as a RIPK3 target and recruiting the RIPK1-RIPK3-MLKL necrosis 'attack' complex to mitochondria.
Synonyms: MGC5352; BXLBv68
Tractability: Antibody: UniProt predicts a signal peptide or a membrane-spanning region. PROTAC: ubiquitination databases record sites on it; its protein half-life has been measured.
Target class: Enzyme; Hydrolase
Gene: Protein-coding gene on chromosome 12 (132,710,786 to 132,722,734, forward strand). Ensembl gene ENSG00000247077.
Subcellular location: Mitochondrion outer membrane; Mitochondrion inner membrane
Subcellular location (Human Protein Atlas): Mitochondria
Pathways (Reactome):
Autophagy: Receptor Mediated Mitophagy
Metabolism: Regulation of pyruvate metabolism
Gene Ontology:
Molecular function: protein binding; protein serine/threonine phosphatase activity
Biological process: macroautophagy; negative regulation of cold-induced thermogenesis; positive regulation of mitochondrial fission; necroptotic process
Cellular component: mitochondrial inner membrane; mitochondrion; mitochondrial outer membrane; mitochondrial membrane
Genetic constraint (gnomAD): Loss-of-function variants: 25 observed, 25.02 expected, observed/expected ratio (o/e) 1, 90% interval 0.73 to 1.39. The synonymous counts are far from expectation, so gnomAD's model fits this gene poorly and the ratio says little. Missense variants: 384 observed, 372.46 expected, observed/expected ratio (o/e) 1.03, 90% interval 0.95 to 1.12. Synonymous variants: 201 observed, 157.73 expected, observed/expected ratio (o/e) 1.27, 90% interval 1.13 to 1.43.
Homologues: Orthologues: chimpanzee PGAM5 (100% identical), macaque PGAM5 (99% identical), pig PGAM5 (94% identical), mouse Pgam5 (93% identical), rat Pgam5 (93% identical), guinea pig PGAM5 (89% identical), rabbit PGAM5 (79% identical), dog PGAM5 (77% identical), zebrafish pgam5 (64% identical), Drosophila melanogaster Pgam5 (46% identical), Caenorhabditis elegans pgam-5 (44% identical), Drosophila melanogaster Pgam5-2 (39% identical).
Diseases named in the same sentence as PGAM5 in open-access papers:
PGAM5 is named in the same sentence as 99 diseases in open-access papers, as found by Europe PMC text mining. Sharing a sentence is not in itself a finding about the gene and the disease. The quoted sentences say what the papers report.
hepatocellular carcinoma (15 papers, 2018 to 2026). A malignant tumor that arises from hepatocytes. "Upregulated PGAM5 expression level is associated with several forms of cancer, including hepatocellular carcinoma (HCC), human colorectal cancer (CRC) and adenocarcinoma." (PMID 41064959, 2025). "The mitochondrial membrane protein phosphoglycerate mutase 5 (PGAM5) is a protein of interest in the complex transition from hepatic steatosis to hepatocellular carcinoma." (PMID 42146432, 2026). "Increased expression of PGAM5 in hepatocellular carcinoma is correlated with reduced patient survival." (PMID 42146432, 2026). "Treatment of the hepatoma and hepatocellular carcinoma cell lines, HepG2 and HuH7, respectively, with the novel PGAM5 inhibitor LFHP-1c inhibited cell growth after 24 h at all concentrations tested." (PMID 40361499, 2025). "Overexpression of PGAM5 is correlated with a poor prognosis in hepatocellular carcinoma, colon cancer, and melanoma." (PMID 37835490, 2023). "Overexpression of tumoral phosphoglycerate mutase 5 (PGAM5) is correlated with reduced survival in hepatocellular carcinoma, as well as other cancers." (PMID 37835490, 2023). "In hepatocellular carcinoma, silencing of PGAM5 reduces growth, which has been attributed to decreased mitophagy and enhanced apoptosis." (PMID 37835490, 2023). "This is the first time that PGAM5 expression has been correlated to exogenous fatty acid import in hepatocellular carcinoma." (PMID 37835490, 2023). "By inhibiting apoptotic signalling, PGAM5 (PGAM family member 5) has been shown to be a poor prognostic factor for patients with hepatocellular carcinoma, which is consistent with our findings." (PMID 35293027, 2022). "The aim of this study was to explore the clinical significance and potential biological functions of PGAM5 in hepatocellular carcinoma." (PMID 30250224, 2018). "We learned that by eliminating PGAM5 expression, lipid droplet accumulation was reduced in hepatocellular carcinoma and that this may be due to reduced fatty acid uptake." (PMID 37835490, 2023). "The mitochondrial membrane protein phosphoglycerate mutase 5 (PGAM5) is overexpressed in hepatocellular carcinoma and may play a role in lipid metabolism." (PMID 37835490, 2023). "We sought to identify whether deletion of PGAM5 modulated lipid droplet accrual in hepatocellular carcinoma." (PMID 37835490, 2023). "PGAM5’s role in hepatocellular carcinoma includes regulation of fatty acid metabolism, which may be related to expression of the fatty acid transporter, FABP1." (PMID 37835490, 2023). "The aim of our research study was to determine whether the expression of PGAM5 modified fatty acid uptake and lipid droplet accumulation in hepatocellular carcinoma cells." (PMID 37835490, 2023). "Our data suggest that PGAM5’s role in hepatocellular carcinoma includes regulation of fatty acid metabolism, which may be implemented through expression of the fatty acid transporter, FABP1." (PMID 37835490, 2023). "We found that deletion of PGAM5 attenuates hepatocellular carcinoma cell growth and ATP production." (PMID 37835490, 2023). "Research indicates that PGAM5 is often overexpressed in various cancers, including hepatocellular carcinoma (HCC) and colorectal cancer (CRC), with its high expression correlating with poor prognosis." (PMID 39941813, 2025). "Background/Objectives: Upregulation of phosphoglycerate mutase 5 (PGAM5) is correlated with reduced survival outcomes in hepatocellular carcinoma (HCC)." (PMID 40361499, 2025). "At the protein level, SIRT2 activates malic enzyme 1 (ME1) activity by deacetylating PGAM5, thereby promoting lipid synthesis and hepatocellular carcinoma (HCC) cell proliferation." (PMID 39930129, 2025). "Moreover, PGAM5 depletion inhibits hepatocellular carcinoma cell growth and promotes apoptosis." (PMID 36523972, 2022). "Aberrant expression of SND1 and PGAM5 predicts poor outcomes in hepatocellular carcinoma (HCC) patients." (PMID 35433434, 2022).
hepatocellular carcinoma (continued). "In conclusion, our study determined the prognostic and immunological roles of necroptosis‐related molecules such as TRAF2, PGAM5, ATG16L1, CADR9, PCYT1A, PARP2 and TLR2 in hepatocellular carcinoma." (PMID 35293027, 2022).
Parkinson disease (14 papers, 2013 to 2025). A progressive degenerative disorder of the central nervous system characterized by loss of dopamine producing neurons in the substantia nigra and the presence of Lewy bodies in the substantia nigra and locus coeruleus. "In neurodegenerative diseases, such as Parkinson's disease, aberrant PGAM5 activity has been linked to impaired mitochondrial quality control and increased neuronal vulnerability." (PMID 41064959, 2025). "PINK1 and PGAM5 are known to play essential roles in maintaining mitochondrial integrity and homeostasis and have been linked to both Parkinson’s disease and defects of spermatogenesis." (PMID 37505079, 2023). "A previous study disclosed that PGAM5-deficient mice presented with a Parkinson’s-like movement phenotype, and PGAM5 exerted cytoprotective effects on dopaminergic neurons." (PMID 36389083, 2022). "PGAM5 phosphatase activity is required for PINK1 stabilization as well as PINK1/Parkin-mediated mitophagy, and PGAM5-deficient mice develop Parkinson’s disease." (PMID 28401475, 2018). "We aimed to examine whether plasma-derived phosphoglycerate mutase 5 (PGAM5) can be a biomarker for Parkinson’s disease (PD) diagnosis as well as its association with the severity of motor/non-motor manifestations of PD." (PMID 36389083, 2022). "Loss of PGAM5 inhibits mitophagy in vitro, and leads to Parkinson’s-like symptoms in mice." (PMID 28891792, 2017). "Consistent with this line of evidence, increased PGAM5 was shown to promote neuroprotection in mice models of Parkinson’s disease." (PMID 37221611, 2023). "PGAM5 deficiency disrupts PINK1-mediated mitophagy and led to a Parkinson’s-like phenotype involving dopaminergic neurodegeneration and mild dopamine loss in a Pgam5-deficient mouse model in vivo." (PMID 26807733, 2016). "Our new data are also consistent with our previous observations that Pgam5 knockout mice manifest a Parkinson’s disease phenotype due to dopamine neuron degeneration." (PMID 26807733, 2016). "More analysis of the functional interaction between PGAM5 and PINK1 would reveal the role for PGAM5 in the mitochondrial quality control and possibly in the pathogenesis of Parkinson’s disease." (PMID 23443160, 2013). "Given that mitochondrial transplantation is beneficial for neurological diseases such as Parkinson’s disease and ischemic stroke, it is probably that induction of PGAM5 cleavage may also be beneficial for neurological diseases other than TBI." (PMID 37221611, 2023). "Loss of PGAM5 causes accumulation of damaged mitochondria that worsen necroptosis, dopaminergic neuron degeneration, and defects in growth and cell survival, establishing a molecular link between PGAM5 and the pathogenesis of Parkinson’s disease and cardiac diseases." (PMID 35921890, 2022). "Harnessing the effect of PGAM5 deletion in anti-oxidation but preventing its undesired effect in senescence could be beneficial in age-related diseases, including Parkinson’s disease and AMD." (PMID 32439975, 2020). "Notably, PGAM5 knockout in mice leads to a more severe Parkinson’s disease-like phenotype than observed for PINK1 knockout, suggesting that PGAM5 has multiple functions that support dopaminergic neuron survival." (PMID 30705304, 2019). "This study was aimed at evaluating the effects of phosphoglyceromutase 5 (PGAM5) overexpression in the cellular model of Parkinson`s disease, 6-hydroxydopamine (6-OHDA)-treated differentiated human embryonic mesencephalic cells of the Lund Human Mesencephalic (LUHMES) cell line." (PMID 25986246, 2015).
liver cancer (4 papers, 2022 to 2026). An epithelial or non-epithelial malignant neoplasm that arises from the liver. "In this study, we demonstrate that loss of PGAM5 alters the bioenergetic landscape of liver cancer by promoting mitochondrial oxidant injury and suppressing the glycerophospholipid and lysophospholipid pathways, leading to accumulation of the bioactive phospholipid lysophosphatidylcholine." (PMID 42146432, 2026). "Additionally, the association of SND1 and PGAM5 with liver cancer patients was further determined by prognostic analyses." (PMID 35433434, 2022). "The phosphoglycerate mutase 5 (PGAM5) protein is upregulated in liver cancer, and its expression is correlated with reduced survival." (PMID 40361499, 2025). "In this study, we found that SND1 promotes liver cancer through PGAM5-mediated Drp1S637 dephosphorylation and mitophagy." (PMID 35433434, 2022). "Likewise, Staphylococcal nuclease domain-containing protein 1 (Snd1) localizes to the mitochondria and promotes PGAM5-mediated mitophagy and liver cancer progression." (PMID 39063217, 2024). "In liver cancer, the deacetylase SIRT2 deacetylates the lysine K191 site of PGAM5, stimulating the protein phosphatase activity of PGAM5." (PMID 39063217, 2024). "PGAM5, in turn, dephosphorylates and activates malic enzyme 1 (ME1), leading to lipid accumulation and liver cancer cell proliferation." (PMID 39063217, 2024). "Although a decrease in liver cancer cell viability was identified, the effect was independent of PGAM5." (PMID 40361499, 2025). "Finally, Person correlation analysis revealed that SND1 is significantly and positively coexpressed with PGAM5 according to the liver cancer database of TCGA, and SND1 thus positively regulates mitophagy through PGAM5." (PMID 35433434, 2022). "Interestingly, in liver cancer, PGAM5 dephosphorylates the total level of ME1 without altering the dephosphorylation of S336 ME1." (PMID 39063217, 2024). "We applied the novel PGAM5 inhibitor, LFHP-1c, to cell-based models of liver cancer, both with and without PGAM5 expression." (PMID 40361499, 2025).
lung cancer (4 papers, 2018 to 2024). A malignant neoplasm involving the lung. "Our data suggests that the expression of PGAM5 in lung cancer is associated with specific macrophage phenotypes and patient survival." (PMID 30526542, 2018). "We speculate that products from macrophages stimulated by PGAM5 may affect epithelial cell function and may account, at least in part, for the increased risk of lung cancer in patients with COPD." (PMID 30526542, 2018). "In GSE 31210, PGAM5 expression was negatively correlated with the macrophage ‘module 36’ (similar to signature of monocytes activated by tumour necrosis factor + Pam3CSK4 + prostaglandin E2) expression in lung cancer, which itself is inversely associated with mortality." (PMID 30526542, 2018). "For example, both the mRNA and protein expression of PGAM5 were much higher in lung cancer tissues than in normal tissues." (PMID 36523972, 2022). "The level of expression of PGAM5 in lung cancer itself cannot therefore explain why patients with COPD and NSCLC have the worse outcome." (PMID 30526542, 2018). "The expression of PGAM5 in lung cancer was correlated with specific macrophage phenotypes, one of which was associated with lung cancer mortality." (PMID 30526542, 2018).
myocardial infarction (4 papers, 2016 to 2021). Gross necrosis of the myocardium, as a result of interruption of the blood supply to the area, as in coronary thrombosis. "PGAM5 promotion of mitophagy may represent a therapeutic target for stroke, myocardial infarction and other diseases caused by oxidative damage and necroptosis." (PMID 26807733, 2016). "Blockade of mitochondria-mediated cell death through deletion of PGAM5 was shown to improve mitochondrial quality control and reduce myocardial infarction size." (PMID 34211623, 2021). "Consistently, whole‐body deletion of the mitophagy regulator Pgam5 (phosphoglycerate mutase family member 5) worsens the pathological outcome of myocardial infarction, inasmuch as it promotes events of necroptotic cell death." (PMID 34459017, 2021). "Compounds mimicking this binding event could be of potential therapeutic interest in the treatment of stroke, myocardial infarction, and other diseases by stimulating the mitophagy-promoting functions of PGAM5." (PMID 30705304, 2019).
pulmonary fibrosis (4 papers, 2020 to 2023). Chronic progressive interstitial lung disorder characterized by the replacement of the lung tissue by connective tissue, leading to progressive dyspnea, respiratory failure, or right heart failure. "Phosphoglycerate mutase family member 5 (PGAM5), a mitochondrial protein with a crucial role in mitochondrial dynamics and programmed cell death, may also contribute to the pathogenesis of pulmonary fibrosis." (PMID 35749794, 2022). "Phosphoglycerate mutase family member 5 (PGAM5), an important regulator of mitochondrial homeostasis in pulmonary fibrosis, impairs mitochondrial integrity at the functional and structural levels." (PMID 36825939, 2023). "Phosphoglycerate mutase family member 5 (PGAM5), a mitochondrial protein, regulates mitochondrial homeostasis and participates in lung fibrosis." (PMID 32724454, 2020). "In addition, previous studies have shown that resveratrol could ameliorate pulmonary fibrosis by increasing miR-21-5p levels and that miR-21-5p suppressed mitophagy to alleviate hyperoxia-induced ALI by directly targeting PGAM5." (PMID 37937296, 2023).
Stroke (4 papers, 2016 to 2019). Sudden impairment of blood flow to a part of the brain due to occlusion or rupture of an artery to the brain. "In oxidative damage and necroptosis-dependent stroke, PGAM5 could drive pathology, and thus targeting PGAM5 may be of benefit." (PMID 30140326, 2018).
diabetic cardiomyopathy (3 papers, 2022 to 2024). Diabetic cardiomyopathy is a disorder of the heart muscle in people with diabetes. "Our research endeavors to elucidate the roles of Pgam5 and Phb2 in modulating the evolution of diabetic cardiomyopathy and its underlying mechanisms." (PMID 38818468, 2024). "Firstly, while the study provides crucial insights into the roles of Pgam5 and Phb2 in diabetic cardiomyopathy, it primarily relies on in vitro models." (PMID 38818468, 2024). "This study aims to elucidate the roles of Phosphoglycerate Mutase Family Member 5 (Pgam5) and Prohibitin 2 (Phb2) in the context of hyperglycemia-induced myocardial dysfunction, a critical aspect of diabetic cardiomyopathy." (PMID 38818468, 2024).
gastric cancer (3 papers, 2023 to 2024). A primary or metastatic malignant neoplasm involving the stomach. "Inhibition of necroptosis by different inhibitors and PGAM5 knockdown attenuated GA-induced cell death in gastric cancer cell lines, thereby attenuating GA-caused cell proliferation inhibition." (PMID 37588664, 2023).
Hepatic steatosis (3 papers, 2022 to 2026). Steatosis is a term used to denote lipid accumulation within hepatocytes. "In this study, we employed PGAM5 global-knockout (GKO) mice fed with a high fat high fructose (HFHF) diet and a methionine choline deficient (MCD) diet to investigate the effects of PGAM5 on hepatic steatosis, inflammation and early fibrosis." (PMID 37605246, 2023). "Thus, a decreased capacity for fatty acid oxidation in diet-induced fatty liver disease is closely associated with PGAM5-mediated mitochondrial oxidative stress." (PMID 39285950, 2022). "Knockout of PGAM5 markedly improved hepatic NAS score primarily by reducing hepatic steatosis." (PMID 37605246, 2023). "However, whether PGAM5 affects hepatic steatosis and NASH was unknown." (PMID 37605246, 2023).
injury (3 papers, 2022 to 2023). Damage inflicted on the body as the direct or indirect result of an external force, with or without disruption of structural continuity. "In a mouse model of septic kidney injury, loss of Pgam5 inhibited inflammation by preventing Bax dephosphorylation-mediated release of mitochondrial DNA 54-56." (PMID 37781037, 2023).
ischemia (3 papers, 2016 to 2024). A hypoperfusion of the BLOOD through an organ or tissue caused by a PATHOLOGIC CONSTRICTION or obstruction of its BLOOD VESSELS, or an absence of BLOOD CIRCULATION. "We explanted hearts from both Pgam5 WT and KO mice; induced ischemia for 25 minutes followed by 90 minutes of reperfusion, and evaluated hemodynamic function as well as histologically apparent infarct size." (PMID 26807733, 2016).
ischemic stroke (3 papers, 2023 to 2026). A stroke disorder caused by obstruction of blood flow to the brain, due to thrombotic (local blood clot formation) or embolic (due to a blood clot or other material traveling from another site) event. "In summary, the neuroprotective effect of EA against ischemic stroke might be achieved by inhibiting neuronal apoptosis through PGAM5/FUNDC1-dependent mitophagy." (PMID 41933402, 2026). "PGAM5 is likely to be a target for the therapy of ischemic stroke." (PMID 38637126, 2024).